RAC1 (Rac family small GTPase 1)
Diseases named in the same sentence as RAC1 in open-access papers (continued):
Sharing a sentence is not in itself a finding about the gene and the disease.
tumor (continued). "Thus Tpm4.1 plays an important role in blocking invasive behaviors through Rac1-myosin IIB signaling and our findings suggest that decreased expression of Tpm4.1 might play a crucial role during tumor progression." (PMID 28431393, 2017). "The previous study identified that Rac1 could binding to SET, also known as TAF1β (template activating factor 1β), and suppress the function of PP2A by increasing the phosphorylation level in tumor cells." (PMID 28057023, 2017). "In addition to Rac1, GLS2 may interact with other proteins to regulate their functions, which in turn contributes to GLS2’s function in tumor suppression." (PMID 26751560, 2016). "Therefore, antagonists that disrupt the binding of IQGAP1 to RAC1 and/or CDC42 could prevent tumor invasion, proliferation, and migration and could act as specific chemotherapeutic agents." (PMID 27815503, 2016). "By inhibiting Rac1 activity and suppressing the corresponding downstream effects, such as F-actin polymerization and VEGF expression, TIPE2 functions as a tumor suppressor to control the migration, invasion of NSCLC cells and the angiogenesis in tumor microenvironment." (PMID 27556698, 2016). "Finally, AZA197, another recently developed Cdc42 inhibitor which appears not to inhibit Rac1 activity has shown some efficacy in reducing tumor size in a xenograft model of colon cancer." (PMID 27104658, 2016). "In co-culture system, tumor cells produced time-dependent increases in transendothelial passages of FITC-dextran, after 24-h, the transendothelial passages were potentiated by approximately 2.6-fold, whereas knockdown of Rac1 in HUVEC attenuated this effects by approximately 30%." (PMID 25991673, 2015). "In the normal mucosa, this pathway serves as a tumor-suppressor, by antagonizing the canonical Wnt-β-catenin signaling pathway, whereas in advanced tumors it triggers cell migration/invasion by enhancing PI3K-Akt and Rac1 pathways and the formation of actin stress fibers." (PMID 26126266, 2015). "In addition, Rac1 did not appear to be involved in the regulation of transcapillary migration of tumor cells or the growth of brain metastatic tumors." (PMID 24804765, 2014). "Redox-sensitive molecules such as members of the Rat sarcoma (RAS) family of small GTPases, Ras, Rho, and Rac1, have been related to increased vascular permeability that, at the level of the blood-brain barrier (BBB), may facilitate the entry of metastatic tumor cells into the brain." (PMID 24804765, 2014). "Importantly, none of these processes were affected when Rac1 was depleted or deleted in the tumor endothelium of adult wild-type mice." (PMID 20339539, 2010). "Importantly, however, our findings demonstrate that the involvement of Rac1 in 3D endothelial cell migration is not as critical as originally thought and this is likely to reflect the reason for the normal tumor angiogenesis in Rac1-depleted mice in vivo." (PMID 20339539, 2010). "In contrast, the requirement for Rac1 in tumor growth and angiogenesis becomes important when endothelial β3-integrin levels are reduced or absent: the enhanced tumor growth, tumor angiogenesis and VEGF-mediated responses in β3-null mice are all Rac1-dependent." (PMID 20339539, 2010). "Thus the most logical assumption is simply that Rac1 is not involved in tumor angioegenesis in vivo unless β3-integrin is absent." (PMID 20339539, 2010). "Whereas Rac1 protein level was not significantly related to proliferation, highly proliferative tumours (i.e. >20% MIB-1 positive cells) showed a significant increase in the level of RhoA-like proteins as compared to tumours with low proliferation index (i.e. MIB-1 <5%) (P<0.05)." (PMID 12237774, 2002). "Future studies should investigate whether OC disrupts this PAR-2/RAC1/β-catenin axis in IDH-mutant CHS models, leveraging its dual capacity to downregulate PAR-2 and preserve repressive H3K27me3 epigenetic marks to counteract CpG island hypermethylation at tumor suppressor loci such as CDKN2A." (PMID 40564985, 2025).
tumor (continued). "Our results revealed similar tumor latencies for Rac1b−/−;MMTV-NIC, Rac1b+/−;MMTV-NIC and Rac1b+/+;MMTV-NIC mice, indicating that the tumor latency phenotype observed in Rac1flox/flox;MMTV-NIC and Rac1flox/+; MMTV-NIC mice is due to the loss of Rac1, not Rac1b." (PMID 36599922, 2023). "This could indicate that Rac1 is a key protein in the lack of treatment responsiveness and/or provides compensatory resistance mechanisms to standard therapy such as chemo- and radiotherapy, as described in other tumor types." (PMID 36230732, 2022). "The unexpected finding that E-cadherin is internalized by Rac1 activation without significant dissociation of catenins in primary keratinocytes is consistent with data from tumor cell lines that the disruption of cell–cell adhesion may not use the classical internalization routes." (PMID 33914026, 2021). "Indeed, elevated mRNA expression may not be the best determinant of tumor Rac1 activity for two major reasons." (PMID 31344967, 2019). "Our previous research demonstrated that by directly binding with Rac1-GTPases, murine TIPE2 dictates the strength of phagocytosis and oxidative burst in innate immunity, while human TIPE2 could inhibit various malignant behaviors of tumor cells and suppress tumor metastasis." (PMID 30186591, 2018). "Based on the exciting observation that RAC1b functions as an endogenous inhibitor of RAC1, we propose a model on how the relative abundance or activity of RAC1 and RAC1b in the tumor cells may determine their responses to TGF-β and, ultimately, the metastatic capacity of the tumor." (PMID 28499439, 2017). "The hypothesis that Rac1b acts as an antimigratory factor by antagonizing protumourigenic Rac1 might be tested in mouse models of PDAC development or in tumour tissues from patients with different/earlier disease stages since in this study only tumours with the stage T3N1M0 were analyzed." (PMID 24378395, 2014). "Importantly, we show that targeting Rac1 can effectively block the lung metastatic and tumor initiating activities of both SP and non-SP NSCLA cells, and such benefits may apply to the CD133+/CD133− tumor initiating populations." (PMID 21347385, 2011). "Hyperactive Rac1 could therefore increase basal growth through its (TGF-β/Smad-independent) growth promoting effect and, at the same time, protect tumour cells, which have not yet accumulated inactivating mutations in the TGF-β pathway, from exaggerated growth restraints by TGF-β." (PMID 21624123, 2011). "However, a precise role for Rac1 in tumor angiogenesis has never been addressed." (PMID 20339539, 2010). "Here we report that RAC1B, but not the conventional RAC1 isoform RAC1A, promotes tumor development, stabilizes EGFR, and can serve as an ideal therapeutic target in EGFR‐mutant LUAD." (PMID 40548642, 2025). "Oncogenes with expression scaling with amplification, such as RAC1 and CDK4, were less methylated when amplified (P = 1.53 × 10−5 and 5.63 × 10−4, respectively; Mann–Whitney U-test) compared to non-amplified tumor regions." (PMID 40931149, 2025). "Normal liver tissue had negative or medium NCKAP1, RAC1, RPN1, and WASF2 IHC staining, while tumor tissues had medium or strong staining." (PMID 38968580, 2024). "Conversely, one target gene, RAC1, showed a negative correlation with ESR2 expression patterns in those tumor types." (PMID 39201394, 2024). "RAC1 and RAC1B are overexpressed in CRC and associated with worse prognosis compared to tumors that do not have RAC1 or RAC1B overexpression, suggesting there is a role for these proteins in CRC biology and tumor progression." (PMID 39001533, 2024). "The inability of RAC1WT to restore the tumor formation ability is consistent with the conclusion that RAB4A plays a major role in the activation of RAC1; therefore, only the activated RAC1 can perform the function without the help of RAB4A." (PMID 36307864, 2022).
tumor (continued). "The effects of tumor-conditioned medium on control cells were a quite pronounced reduction on the expression of FAK and Arp 2/3 proteins, with no significant changes in Rac1 and actin filaments." (PMID 34421610, 2021). "Radiation treatment together with RAC1 targeting (NSC27366) protected normal intestinal cells, but not tumor cells, by supporting cell cycle and reducing ROS production remarkably." (PMID 33406731, 2021). "In these tumor entities, RAC1B is also a prominent example for a splice product that is tumor-protective as opposed to the parental isoform, RAC1." (PMID 33567745, 2021). "In our current study, we found that the overexpression of Porf-2 reduced the activated Rac1 levels in tumor cells, but not Cdc42, demonstrating that Porf-2 acts as a Rac1-specific GAP in tumor cell migration, which is consistent with previous reports." (PMID 32676454, 2020). "Because of the importance of Rac1 in apoptosis, and because RCC2 expression effectively blocked Rac1 activation, it is not surprising that tumor cells with forced RCC2 expression reacted differently to drug-induced apoptosis." (PMID 29321004, 2018). "Remarkably, constitutive activation of Rac1 in K14 HPV-8/K14 L61Rac1 transgenic mice did not result in an increased frequency of SCCs, suggesting that the role of Rac1 in skin carcinogenesis is primarily growth promoting and not transforming." (PMID 27506937, 2016). "Indeed, among the most upregulated genes in FAT4 knockdown cells we found ARHGEF6, encoding for the guanine nucleotide exchange factor αPIX that activates Rac1 and Cdc42 GTPases and ARHGDIB, a negative modulator of the RhoA tumor suppressor." (PMID 39478125, 2024). "We presented here that Rac1 activity but not RhoA or Cdc42 was increased significantly by PA treatment through CD36-Src-Akt signaling pathway, suggesting that Rac1 participated in triggering actin-remodeling and promoting LUAD tumor metastasis." (PMID 37612265, 2023). "Our data showed that RAC1-K5R failed to rescue the MG53-mediated inhibiting effect on cell proliferation, colony formation and migration, which verified that MG53 exerted its anti-tumor effect via its modification of RAC1 at Lys5 residue." (PMID 35858925, 2022). "However, Rac1 proved important in CSC activity, in both the side population (SP) cells and non-SP cells within the tumor in NSCLA (Non-Small Cell Lung Adenocarcinoma)." (PMID 27597870, 2016). "Indeed, the negative dominant expression of Rac1 or Cdc42 (Rac1–N17 or Cdc42–N17) in kidney cells (MDK cells) was shown to decrease cell–to–cell adhesion, explaining the reduced clonogenic ability and tumor cell density." (PMID 35743115, 2022).
infection (126 papers, 2008 to 2025). The state of being infected such as from the introduction of a foreign agent such as serum, vaccine, antigenic substance or organism. "In conclusion, our results reveal a new role of RAC1 in enhancing myometrial contraction in the pathogenesis of infection-associated PTB." (PMID 36018772, 2022). "This aside, it is still feasible that Rac1 mislocalisation caused by β-PIX is something that PAK is able to overcome during infection." (PMID 34460869, 2021). "Activation of Rac1 was significantly higher in APE1-deficient cells compared to control cells following infection with S. Typhimurium and AIEC." (PMID 33603730, 2020). "We, therefore, surmise that the main reason for reduced infection rates by blocking Cdc42 or Rac1 is reduced virion trafficking in the host cell, caused by the inability of EHV-1 to induce α-tubulin acetylation." (PMID 32645930, 2020). "For example, melatonin reduces migration of endothelial cells through inhibition of Rac1 activation (39, ), whereas infection of gastric epithelial cells with EPEC reduces cell migration associated with Rac1 inhibition." (PMID 30066727, 2018). "Here, we describe how Wnt5A, a representative non-canonical Wnt programs macrophages for host defense against infections by leading bacterial pathogens utilizing host cytoskeleton and the associated Rac1—Disheveled coupled autophagy circuit." (PMID 29686674, 2018). "Infection of S. aureus causes the recruitment of active Rho GTPases Rac1 and PI3K to the TLR2 cytosolic domain." (PMID 28165033, 2017). "However, infection by the EF::RDTND-RID strain infection led to a significant reduction in the association between the key component Rac1 and these subunits, resulting in NOX2 inactivation and inhibition of ROS generation." (PMID 39043696, 2024). "Since Rac1 and Rab35 were able to recover the cell shape and migration phenotypes produced by Prpk deficiency, we also examined the rate of survival to infection in flies co-expressing each protein with the Prpk-IR construct." (PMID 35721516, 2022). "At this timepoint, only 7–10% of bacteria are intracellular, thus the recruitment of Rac1 and Cdc42 (8.6 ±0.9% and 6.7 ±1.3% respectively) reflects the transient association of these with nearly every invasion-competent EB at 10 minutes post-infection." (PMID 29727463, 2018). "Protein samples were prepared 24 h post-infection and western blot analysis was performed using anti-Arp2, anti-Rac1, anti-Wasp, and anti-Profilin antibodies." (PMID 39949767, 2025). "Western blotting analysisrevealed that the activities of Cdc42-GTPase and Rac1-GTPase were transientlyinduced by PEDV during the initial phases of infection at 30 min." (PMID 40094365, 2025). "Curiously, when we performed RhoGTPase inhibition in serum-free (in the case of RhoA, B and C inhibitor) or low serum (in the case of the Rac1 inhibitor) media, the difference in infection between shScr and shMyo9b #3-expressing U937 cells was reduced." (PMID 40167026, 2025). "By integrating immune receptor signals, activated Rac1 regulates the directed movement and adhesion of immune cells, which is vital for blood leukocyte chemotaxis and tissue extravasation during infections." (PMID 40041147, 2025). "Gram-positive and gram-negative bacteria elicit immune responses that manifest as changes in white blood cell counts and are linked to changes in Rac1•GTP levels in leukocytes, triggering their activation and mobilization to sites of infection." (PMID 40041147, 2025). "Only the cells activated by E. coli exhibited a significant difference in Rac1•GTP content per unit cell compared to infection by the other bacterial species." (PMID 40041147, 2025). "The range of Rac1•GTP-mediated immune responses to infection was determined by plotting the Rac1•GTP levels in cell populations of activated PBMCs and PMNs from representative serial patient samples and found to be ≥ 3-fold above controls in samples." (PMID 40041147, 2025).
infection (continued). "While the molecularevents downstream of RAC1 that enable macrophage phagocytosis have been revealed indetail, how the activation of RAC1 is regulated in macrophages duringMtb infection is far from understood." (PMID 39287444, 2024). "By contrast, murine macrophages exhibited increased Rac-1 expression after infection with L. braziliensis and L. infantum, while L. amazonensis infection was found to increase Cdc42 expression." (PMID 37576604, 2023). "CCR has also been shown to be an effector of Rac1, a small GTPase operating within plant defence signalling pathways and is an elicitor of the hypersensitive response to infection by Tobacco mosaic virus." (PMID 38023930, 2023). "Herein we observed increased Rac1 expression in BMDMs infected with L. braziliensis and L. infantum; by contrast, infection by L. amazonensis resulted in increased Cdc42 expression." (PMID 37576604, 2023). "On the other hand, Rac1 interacts with Nox1 and Nox2 in the signaling pathway to produce ROS required for infection-related development and pathogenicity in P. oryzae." (PMID 37108909, 2023). "The Rho GTPase Rac1 was shown to play an important role in infection by both T. gondii and P. falciparum." (PMID 35889089, 2022). "Recent evidence also demonstrated the requirement of actin remodeling proteins ARP3 and RAC1 in the later stages of infection as well as an actin–E2 interaction, indicating the CPV-II trafficking to the PM are actin dependent." (PMID 36137747, 2022). "The effector primarily targets the GAP domain of ABR to suppress Rac1 and Cdc42, host cell cytotoxicity, bacterial invasion, and filopodium formation at infection sites." (PMID 36219160, 2022). "The mycobacteria activated the p38K/JNK/b1-integrin/Rac1 signaling cascade in the frame of the infection." (PMID 35740379, 2022). "Based on our observation that constitutively active Rac1 restored PA phagocytosis in AMs lacking PAR2 expression, we surmised that rescuing constitutive Rac1 would clear infection and thereby mitigate lung injury." (PMID 36204227, 2022). "Once in the cells, the bacteria produce a toxin CNF1 (cytotoxic necrotizing factor type, which constitutively activates different Rho GTPases, including Rac1 critical to phagocytosis, to promote further infection." (PMID 35740379, 2022). "During infection, C. jejuni activated the Rho family small GTPase Rac1 signaling pathway, which modulates actin remodeling and promotes the internalization of this pathogen." (PMID 35310852, 2022). "After interfering with or silencing the Rac1 gene, the infection rate of T. gondii is significantly reduced." (PMID 36080339, 2022). "As the next step, we aimed to study if the expression of cortactin and Vav2 were required for the activation of Rac1 during infection." (PMID 34439396, 2021). "Rac1 and Cdc42 G-LISA kits were used to determine the amount of active (GTP bound) Rac1 and Cdc42 present in the cells after infection." (PMID 33637714, 2021). "The amount of active Rac1 was higher after infection with WT SL in control shRNA cells compared to ELMO1 shRNA cells." (PMID 34719317, 2021). "By contrast, infection with yopEL109A, which has partially reduced RhoA-GAP activity (about 70% of WT YopE) and normal Rac1-GAP activity, caused M cell extrusion similar to WT 37°C and had a Yptb internalization phenotype similar to WT 37°C." (PMID 34793276, 2021). "The inhibitory effect of Rac1 and Cdc42 inhibitors was more pronounced in the case of EHV-1 gH4 and EHV-1 gHS440A, where it resulted in an ~80% (Rac1 inhibitor) and ~95% (Cdc42 inhibitor) reduction of infection." (PMID 32645930, 2020). "We further identified specific steps of the infection process, at which Rac1 and Cdc42 play a crucial role." (PMID 32645930, 2020). "Especially noteworthy pathways in the early phase (2 hpi) of infection included Rac1, TNFα signaling via NFκB and G_α signaling events." (PMID 31906849, 2020).